DDB2 (damage specific DNA binding protein 2)
Diseases named in the same sentence as DDB2 in open-access papers (continued):
Sharing a sentence is not in itself a finding about the gene and the disease.
pancreatic cancer (2 papers, 2022 to 2025). "The expression level of DDB2 in pancreatic cancer tissues and its correlation with patient survival were evaluated using publicly available data." (PMID 36568213, 2022). "Here, we showed that high DDB2 levels seem correlated with better prognosis in patients with pancreatic cancer and sensitize PDAC cells to chemotherapy." (PMID 36568213, 2022). "Moreover, a preclinical study also indicated the essential role of DDB2 in conferring pancreatic cancer cells resistant to radiotherapy." (PMID 41208896, 2025). "Together, our results identify new tumor suppressor functions of DDB2 in pancreatic cancer." (PMID 36568213, 2022). "Through its roles in NER and HR, DDB2 promotes DNA repair following genotoxic stress, enabling cancer cells to survive treatment with DNA-damaging agents such as doxorubicin 17, platinum compounds 45, PARP inhibitors 16, or radiotherapy 46 in breast, colorectal, and pancreatic cancers, respectively." (PMID 41208896, 2025).
radiation injury (2 papers, 2022). Harmful effects of non-experimental exposure to ionizing or non-ionizing radiation in VERTEBRATES. "Up-regulation of FDXR and DDB2 GE indicates risk of mild acute radiation sickness, whereas an up-regulation of FDXR and DDB2 combined with a down-regulation of WNT3 and POU2AF1 predicts severe ARS10,11." (PMID 35680903, 2022). "Specific radiation-sensitive genes (such as FDXR, DDB2, WNT3, POU2AF1) have become well established for biodosimetry purposes and acute radiation sickness (ARS)-prediction." (PMID 35680903, 2022).
anemia (1 paper, 2017). A reduction in the number of red blood cells, the amount of hemoglobin, and/or the volume of packed red blood cells. "The results showed that GTF2H1/P62 and DDB2 presented consecutive significant signals on anemia." (PMID 28924235, 2017).
colon adenoma (1 paper, 2018). An adenoma that arises from the colon. "Besides, colon adenoma and rectal adenoma both demonstrated upregulated mRNA of DDB2 (fold change is 3.159 and 2.890, resp)." (PMID 29568775, 2018).
encephalitis (1 paper, 2022). An acute inflammatory process affecting the brain parenchyma. "In addition, a recent study found that DDB2 is a pathogenic gene for hepatitis and encephalitis." (PMID 36190612, 2022).
Hepatitis (1 paper, 2022). Inflammation of the liver. "Further research in these aspects will broaden our understanding of the multifaceted functions of DDB2 and provide new strategies for treating other human diseases, such as hepatitis." (PMID 36190612, 2022). "In addition, new roles for DDB2 in other diseases, including hepatitis, are also discussed." (PMID 36190612, 2022).
hepatocellular carcinoma (1 paper, 2020). A malignant tumor that arises from hepatocytes. "In this study, we evaluated the association of single-nucleotide polymorphism (SNP) rs1050244 in miRNA target site of DDB2 gene with risk of hepatocellular carcinoma (HCC) among 1073 HCC patients and 1119 cancer-free controls in a southern Chinese population." (PMID 32090112, 2020).
Insulin resistance (1 paper, 2025). Increased resistance towards insulin, that is, diminished effectiveness of insulin in reducing blood glucose levels. "DDB2 directly interacts with progestin and adipoQ receptor 3 (PAQR3), facilitating PAQR3 ubiquitination, consequently enhancing PI3K/AKT axis signaling to ameliorate insulin resistance and mitigate retinopathy in diabetic mice." (PMID 40276708, 2025).
keloid (1 paper, 2025). An irregularly shaped, elevated mark on the skin caused by deposits of excessive amounts of collagen during wound healing. "ROC analytical frameworks were established to evaluate the diagnostic potential of CDK7 and DDB2 as keloid biomarker candidates." (PMID 41347148, 2025). "Through WGCNA and PPI network analyses, we identified two key genes, CDK7 and DDB2, associated with keloid." (PMID 41347148, 2025). "Our findings demonstrate that CDK7 and DDB2 are promising biomarkers for diagnostic and potential therapeutic targets in keloid, providing novel insights into its pathogenesis and offering promising druggable targets." (PMID 41347148, 2025). "Integrated bioinformatics and basic experimental approaches were used in this study to detect and confirm two biomarkers, CDK7 and DDB2, associated with keloid." (PMID 41347148, 2025). "Basic experiments confirmed higher expression of CDK7 and DDB2 in keloid tissue compared to normal skin." (PMID 41347148, 2025). "These experiments verified that CDK7 and DDB2 expression in keloid tissue cells was markedly elevated compared to normal tissues, further supporting the reliability and research value of our analysis." (PMID 41347148, 2025). "The elevated expression of DDB2, a key DNA damage recognition protein, in keloid—a benign fibroproliferative lesion—raises an intriguing question." (PMID 41347148, 2025). "Further validation via qRT-PCR, western blotting, and immunofluorescence confirmed significantly elevated expression of CDK7 and DDB2 in keloid specimens relative to normal specimens." (PMID 41347148, 2025). "In summary, we identified two novel keloid-associated genes, CDK7 and DDB2, through bioinformatics analysis." (PMID 41347148, 2025). "Although the specific molecular mechanism still needs further research, this provides a new perspective for understanding the role of CDK7 and DDB2 in the pathogenesis of keloid." (PMID 41347148, 2025). "Second, the specific roles of CDK7 and DDB2 in keloid pathogenesis are not fully understood and require molecular biology experiments and rigorously designed multicenter studies for validation." (PMID 41347148, 2025). "Based on degree scores, CDK7 and DDB2 were identified as key genes, with their expression levels in keloid and control groups visualized via box plots." (PMID 41347148, 2025). "Finally, we validated our bioinformatics findings by assessing CDK7 and DDB2 expression levels in tissues from six keloid patients and six normal subjects using qRT-PCR, western blotting, and immunofluorescence." (PMID 41347148, 2025). "Lastly, although CDK7 and DDB2 are recognized in oncology research, keloids are not classified as true tumors, necessitating further experimentation to substantiate our findings." (PMID 41347148, 2025). "Currently, research has not clearly found whether CDK7 and DDB2 can affect the pathogenesis of keloid through the TGF-β/Smad signaling pathway." (PMID 41347148, 2025).
Li-Fraumeni syndrome (1 paper, 2017).
lymphoma (1 paper, 2022). A malignant (clonal) proliferation of B- lymphocytes or T- lymphocytes which involves the lymph nodes, bone marrow and/or extranodal sites. "Furthermore, of this gene list, 3 are also in the list of genes with known links to CHK1 (Poli, Rev1, Ddb2) we identified as having altered expression in Eμ-Myc/RelaT505A lymphomas." (PMID 36240065, 2022).
migraine (1 paper, 2023). "Additionally, we note that many significant genes (e.g., AMBRA1, ATG13, ARHGAP1, CKAP5, LRP4, and DDB2) have been associated with migraine, headache, and proinsulin." (PMID 36808568, 2023).
neutropenia (1 paper, 2017). A decrease in the number of neutrophils found in the blood. "Polymorphisms in ERCC2, ERCC6, DDB2, RPA1, POLD1 and POLD3 presented significant association with neutropenia." (PMID 28924235, 2017). "Subgroup analyses in the age of patients ≤ 58 showed that DDB2 and RPA1 presented consecutive significant signals on neutropenia." (PMID 28924235, 2017).
non-small cell lung carcinoma (1 paper, 2022). A group of at least three distinct histological types of lung cancer, including non-small cell squamous cell carcinoma, adenocarcinoma, and large cell carcinoma. "It has been reported that DDB2 is a potential regulator of radiosensitivity in non-small cell lung cancer (NSCLC) cells." (PMID 36190612, 2022).
oral cancer (1 paper, 2020). "To examine the role of DDB2 in BQ-associated HNC, we first examined the expression of DDB2 mRNA in premalignant OSFs, which have high probability to progress to oral cancer, from a BQ-epidemic area using the GEO data set (GSE20170)." (PMID 32722430, 2020).
pancreatic ductal adenocarcinoma (1 paper, 2022). An infiltrating adenocarcinoma that arises from the epithelial cells of the pancreas. "Here, we investigated the unresolved role of DDB2 in pancreatic ductal adenocarcinoma (PDAC)." (PMID 36568213, 2022).
prostate tumors (1 paper, 2017). "First, in our initial assessment of pathology slides of prostate tumors that were immuno-stained for DDB2, NRIP, and AR, we already found that some cribriform tumors had distinct expression patterns for these 3 proteins and thus we decided to clarify it using complete statistical analysis." (PMID 28212551, 2017).
retinoblastoma (1 paper, 2025). A malignant tumor that originates in the nuclear layer of the retina. "The highest agreement between RNA and protein level was observed for DDB2, CHAF1B, and POLD1, which were upregulated in retinoblastoma, and RHO, PDE6A, and CRABP1, which were downregulated." (PMID 40395327, 2025).
virus infection (1 paper, 2010). "In this case, increased expression of DDB2 was noticed 24 hrs following virus infection, whereas the level of cFLIP increased only 36 hrs following virus infection." (PMID 20398405, 2010). "In comparison, HR18 cells that overexpressed β-Gal showed a more modest increase of DDB2 mRNA (1.78 fold) and cFLIP (1.9 fold), indicating that virus infection had a low effect on these cells." (PMID 20398405, 2010).
Xeroderma pigmentosum complementation group E (1 paper, 2021). Xeroderma pigmentosum complementation group E (XPE) is an extremely rare subtype of xeroderma pigmentosum (XP; see this term), a rare photodermatosis predisposing to skin cancers. "This study also showed that the K244E variant of DDB2 responsible for xeroderma pigmentosum complementation group E (XPE) displayed sliding on DNA and was unable to stably bind to damaged sites." (PMID 34805281, 2021).
cancer (56 papers, 2007 to 2025). A tumor composed of atypical neoplastic, often pleomorphic cells that invade other tissues. "DDB2-deficient mice have the high rate to develop malignant tumors compared to their XP-deficient littermates." (PMID 33557942, 2021). "But CDT2 and DDB2 are opposite prognostic factors in kinds of cancers, and the underlining mechanism needs to be elucidated." (PMID 33557942, 2021). "DNA damage-binding protein 2 (DDB2) has been considered a tumor suppressor based on the findings that DDB2-/- mice were not only susceptible to UV-induced carcinogenesis, but also developed spontaneous malignant tumors at a high rate." (PMID 26130719, 2015). "Later studies revealed that DDB2 deficient mouse embryonic fibroblasts or human carcinoma cells are resistant to most DNA damage (IR, chemotherapeutic drugs or E2F1) induced apoptosis." (PMID 23109835, 2012). "In both mouse embryonic fibroblasts and human carcinoma cells, the DDB2 deficiency was found to impair ROS accumulation following DNA damage (UV, Cisplatin or Aclarubicin treatment)." (PMID 23109835, 2012). "Knockdown of DDB2 by small interfering RNA in MCF-7 cells caused a decrease in cancer cell growth and colony formation." (PMID 18431487, 2008). "Previous studies showed that mutations in the DDB2 gene, which lead to a deficiency in the NER system, increased susceptibility to develop cancer and a DDB2 deficiency promoted spontaneous malignant tumors in mice." (PMID 18431487, 2008). "Thus, defects in GG-NER genes (such as XPC and XPE/DDB2) confer cancer predisposition, since accumulating DNA damage causes increased mutation rates in replicating cells." (PMID 37026475, 2023). "Only in N0, DNA (excision-) repair (involved genes: CDKN1A, PPM1D, and DDB2) was predicted to be a downstream function, while molecular networks in N2+ were associated with cancer, as well as injury and abnormalities (among others, downregulation of MSH6, CCNE2, and CHUK)." (PMID 36068491, 2022). "For example, allelic imbalance and loss of heterozygosity at the DDB2 locus (11p12-11) are observed in some HNC samples, suggesting that allelic loss of the DDB2 gene may lead to DDB2 downregulation in cancer cells." (PMID 32722430, 2020). "Also, DDB2 deficient MEFs or human carcinoma cells were refractory to UV, Cisplatin or Aclarubicin induced senescence." (PMID 23109835, 2012). "In addition, knockdown of DDB2 in MCF-7 cells caused a decrease of cancer cell growth and colony formation." (PMID 20398405, 2010). "Together, these findings highlight DDB2 as a key modulator of chemotherapy response and a potential driver of disease progression across multiple cancer types." (PMID 41208896, 2025). "Beyond its role in DNA repair, DDB2 acts as a multifunctional protein in cancer progression, serving as a modulator with dual functions that exhibit both tumor-promoting and tumor-suppressing activities." (PMID 41347148, 2025). "Collectively, these findings identify DDB2 as a novel molecular target of lapatinib and demonstrate that lapatinib can disrupt the DNA-binding capacity of DDB2, promote its degradation, and enhance chemosensitivity in cancers with high DDB2 expression." (PMID 41208896, 2025). "These diverse and sometimes contradictory roles underscore the complexity of DDB2's function in cancer biology." (PMID 41208896, 2025). "Within a hetero-cellular tissue (composed of normal and cancer thyrocytes and potential presence of immune cells), over-expression of genes such is DDB2 accelerates cancer cell proliferation and invasion of the thyroid." (PMID 38790250, 2024).
cancer (continued). "DDB2 expression is downregulated in colorectal cancer (CRC) and other cancers and is closely associated with cancer metastasis." (PMID 37256211, 2023). "Furthermore, DDB2-induced CDT2 degradation may be associated with apoptosis in cancer cells." (PMID 36672781, 2022). "There is a need to further understand the involvement of DDB2, FANCG and FANCD2 with respect to cancer risk, in order to facilitate personalized medicine for the carriers." (PMID 36428697, 2022). "DDB2 appears to have a dual function in cancer, sometimes with tumor suppressor properties and sometimes as an oncogene." (PMID 36281462, 2022). "DDB2 has dual roles in several cancers, either as an oncogene or as a tumor suppressor gene, depending on cancer localization." (PMID 36568213, 2022). "This study aims to provide new targets for treating various diseases, including cancer, and provide theoretical support for further research on DDB2." (PMID 36190612, 2022). "DDB2 is involved in the occurrence and development of cancer by affecting nucleotide excision repair (NER), cell apoptosis, and premature senescence." (PMID 36190612, 2022). "We then summarized multiple recent studies describing the regulatory role of DDB2 as an oncogene or tumor suppressor gene in different cancers, as well as its influence on cancer sensitivity to radiotherapy and chemotherapy." (PMID 36190612, 2022). "Beyond its well established functions in DNA repair, DDB2 appears as a multifunctional protein implied in the development and the progression of various cancers with both anti-oncogenic and pro-oncogenic roles." (PMID 36568213, 2022). "Prior to the identification of the role of DDB2 in cancers, DDB2 has been well described in the NER process and was identified to form an heterodimeric UV-DDB complex with DDB1 protein to initiate DNA repair." (PMID 36568213, 2022). "DDB2 had been already shown as having dual roles in migration and invasion of cancer cells depending on the cancer localization." (PMID 36568213, 2022). "Recently, the potential of DDB2 in the development and progression of various cancers has been described." (PMID 31635251, 2019). "Enhanced DDB2 expression in DDB2-low level models upregulates in vitro cancer cell growth rate and clonogenicity." (PMID 31635251, 2019). "Several studies reported DDB2 as playing a novel function in the development and progression of various cancers." (PMID 31635251, 2019). "DDB2 activity occurs at several stages of carcinogenesis including cancer cell proliferation, survival, epithelial to mesenchymal transition, migration and invasion, angiogenesis, and cancer stem cell formation." (PMID 31635251, 2019). "Several studies reported DDB2 as a negative regulatory factor of cancer cell migration and invasion." (PMID 31635251, 2019). "The DNA repair-independent role of DDB2 in suppressing cancer progression has been widely attributed to its transcription regulatory function." (PMID 29752431, 2018). "In this study, we observed less expression of MnSod mRNA in KO:DDB2 cells, which confirms that the transcription regulatory function of DDB2 observed in cancer cells is conserved in MEFs." (PMID 30410671, 2018). "In summary, the data presented here demonstrate that DDB2 silencing is able to expand the CSC subpopulation by promoting cancer cell dedifferentiation." (PMID 29752431, 2018). "We also observed acute repression of DDB2 protein expression in malignant tongue/larynx SCCs in comparison to normal tissues and cancer adjacent normal tissues (NAT)." (PMID 30410671, 2018).